ATR (ATR checkpoint kinase)
Diseases named in the same sentence as ATR in open-access papers (continued):
Sharing a sentence is not in itself a finding about the gene and the disease.
tumor (continued). "In combination with the ATR inhibitor AZD6738, BOLD-100 exhibited synergistic effects in vitro and enhanced anti-tumor activity in vivo, significantly suppressing tumor growth in a Capan-1 xenograft model." (PMID 40514666, 2025). "Among them, cell cycle inhibitors, including Smads and CDKNs, were down-regulated while CDKs, CCNs, E2Fs ATM, ATR, ERCC6, MCMs, and BRCA1 were up-regulated, consistent with a tumor-promoting effect." (PMID 39759123, 2025). "Combined inhibition of CTPS and ataxia telangiectasia and Rad3-related protein (ATR) exhibits synthetic lethality in MYC-overexpressing cells, promoting cell death in vitro and reducing tumor growth in vivo." (PMID 39852139, 2025). "A semi-mechanistic pharmacokinetic-pharmacodynamic model of tumour growth inhibition was developed to investigate the efficacy of PARP and ATR inhibitors as monotherapies, and in combination." (PMID 39875558, 2025). "Here, the authors identify that CCNE1-amplified gynecological cancer is sensitive to combined PKMYT1 and ATR inhibition via CDK1 activation, resulting in premature mitosis, DNA damage, cell apoptosis and reduced tumour growth and metastasis." (PMID 40169546, 2025). "After DNA damage induction, SLFN11 selectively inhibits the translation of key DDR repair genes (such as ATR and ATM) by mediating tRNA downregulation, thereby impairing the repair capacity of tumor cells." (PMID 40766331, 2025). "Since tumor cells are under constant oncogenic stress, they become addicted to checkpoint signals arising from kinases such as ATR (Ataxia Telangiectasia and Rad3-related protein), Chk1 (checkpoint kinase 1) and Wee1." (PMID 40628724, 2025). "To evaluate the effect of enhanced T cell recruitment through ATR inhibition in a model representing the patient DLBCL immune context, we used primary cell lines derived from patient-derived tumor xenografts (PDXs)." (PMID 40674145, 2025). "Supporting these observations, we found that several kinases involved in DNA damage response, ATM, ATR, and PKCA, showed upregulated kinase activity in sensitized tumor cells following both T cell and TNF treatment." (PMID 41315176, 2025). "Meanwhile, the ataxia telangiectasia and Rad3-related protein (ATR) inhibitor VE-822 exhibits LUAD suppression through a novel OTUD1-FHL1 axis, inhibiting tumor growth both in vitro and in vivo." (PMID 41341386, 2025). "What’s more, DNA damage can enhance the expression of PD-L1, facilitating tumor evasion and hindering the recruitment of CD8 T cells, partly by activating ATM/ATR/CHK1 pathway through IRF1 signaling." (PMID 40740769, 2025). "For example, inhibition of Chk1 in human tumor cells triggers hyperactivation of ATM, ATR, and caspase-2, leading to apoptosis after DNA damage." (PMID 39861152, 2025). "Among ATR inhibitors (ATRi), Ceralasertib (AZD6738) has shown efficacy in preclinical models and clinical trials across various tumor types." (PMID 41387887, 2025). "In two of these calibrated tumour models, HBCx-10 and HBCx-17, the DSB repair via ATR/HR pathway 4 was significantly impaired (def4 > 80%), leading to high synergy with PARPi." (PMID 39875558, 2025). "Based on the synergistic reduction of tumor growth of ATM inhibitor AZD0156 and ATR inhibitor VE-822 with a single dose of 1 × 2 Gy13, we first aimed to enhance this effect with a more clinically relevant RT scheme." (PMID 40883442, 2025). "ATM/ATR inhibitors specifically target key kinases in the DDR pathway, thereby interfering with the cell cycle checkpoint regulatory network in tumor cells." (PMID 41473689, 2025). "The model is calibrated with data generated in a BRCA-wild type HRD positive patient-derived xenograft (PDX) tumour model for PARP inhibitors rucaparib or talazoparib, the ATR inhibitor gartisertib and their combination." (PMID 39875558, 2025). "ATM inhibition impairs the cellular DSB repair via homologous recombination, leading tumor cells to depend on remaining functional compensatory DDR pathways, such as ATR." (PMID 40875525, 2025).
tumor (continued). "By enabling simulation of in vivo tumour growth inhibition with PARP and ATR inhibitors for specific tumour types, the model provides a rational approach to support the optimisation of dosing regimens to stratified populations." (PMID 39875558, 2025). "PARG-depleted cells demonstrate an overreliance on the ATR/CHK1/WEE1 damage response pathway, highlighting a potential therapeutic target for such tumours." (PMID 39135999, 2024). "Our results revealed that combined ATR inhibition, ablative radiotherapy, and ICI increased natural killer cell infiltration in the irradiated flank tumor microenvironment, highlighting enhanced antitumor immune responses." (PMID 39487895, 2024). "ATR inhibitors block this BRCA1-independent function, making tumor cells sensitive to reactivation of PARP inhibition." (PMID 39334297, 2024). "Together, our data reveal that SIRT2 acts as a tumor suppressor by promoting OGG1 transcription and increasing BER efficiency in an ATM/ATR-dependent manner." (PMID 38554113, 2024). "Emerging evidence has shown that concurrent inhibition of Ataxia telangiectasia and Rad3-related protein (ATR) and DNA topoisomerase I (TOP1) can result in durable tumor regression in SCLC characterized by high replication stress." (PMID 39103941, 2024). "Initial findings indicate that the co-administration of ATR and CHK1/2 inhibitors alongside chemotherapy effectively inhibits tumor growth in TNBC." (PMID 38539474, 2024). "Furthermore, inhibitors of ATR such as ceralasertib were among the first DNA damage response inhibitors shown to enhance antitumoral immune responses by modulation of both the T1IFN response in tumor cells as well as direct modulation of CD8+ T cells dysfunction." (PMID 38376927, 2024). "Upon hyperthermia-induced DNA damage, tumor cells utilize two primarily distinct kinase signaling cascades to repair DSBs, including the ATM-Chk2 and ATR-Chk1 axes." (PMID 38419081, 2024). "To investigate how PKMYT1 and ATR inhibition are cooperating to activate CDK1, we measured levels of the CDK1 inhibitory phosphorylation at Thr14 (CDK1-pT14) in cell lines and tumor xenografts." (PMID 38410486, 2024). "The poorly differentiated invasive ductal breast carcinoma is a triploid tumour with copy gains in BRIP1 and ATR and a high number of alternations." (PMID 39702187, 2024). "Preclinical studies have demonstrated that BRG1 inactivation increases tumor invasiveness and enhances sensitivity to targeted agents inhibiting oxidative phosphorylation and drugs targeting EZH2, AURKA, ATR, CDK4, and CDK6." (PMID 39465834, 2024). "Until now, the inhibitor of ATR and CHK1 exhibited good therapeutic effect on tumor in labortary, while the strategy on clinic still recommended the combination therapy of them." (PMID 37153782, 2023). "The regulatory approval of PARPi monotherapy in patients with HRD tumours has massively stimulated research in DDR inhibitors, particularly those targeting ATR and CHK1, which also have the potential to reverse PARPi resistance." (PMID 36606678, 2023). "In preclinical studies, the classical components of cell-cycle progression and DNA-damage repair, such as ATM, DNA-PKcs, ATR, CHK1, CHK2 and WEE1, have shown to be very promising targets for radiosensitizing tumor cells by applying small-molecule inhibitors." (PMID 36313934, 2023). "Obviously, one tumor suppressor, ATF2, is sufficient to regulate the ATR-Chk1 interaction under physiological conditions." (PMID 37237279, 2023). "The tumour growth in CAM was greatly suppressed when treated with the AXL and ATR combination treatment compared to either single agent." (PMID 37349576, 2023).
tumor (continued). "PARP inhibitor application increased the expression of ATR protein and contributed to the restoration of DDR function in tumor cells." (PMID 37305685, 2023). "A tumor-specific effect was also observed in combined treatments of THZ531 and ATR or CHK1 inhibitors." (PMID 37202753, 2023). "DDR kinases, such as ATR and CHK1, are crucial tumor suppressors in eukaryotic cells as they maintain the integrity of the genome and suppress tumorigenesis." (PMID 34519926, 2023). "In an early clinical first-in-human study of another ATR inhibitor, RP-3500, similar modest monotherapy responses were observed in patients with ATM-mutant tumours." (PMID 37627223, 2023). "Patients with higher tumor mRNA levels of both ATR and PrimPol had a lower OS rate than those with KRAS-mutant tumors with lower mRNA levels of both ATR and PrimPol among patients with KRAS-mutant tumors in the LUAD cohort." (PMID 37591859, 2023). "For example, inhibition of ATR with AZD6738 enhanced DDP-induced DNA damage in HNSCC cells, thereby improving the sensitivity of tumor cells to DDP." (PMID 36864456, 2023). "This demonstrated that the ATR inhibitor, VX-970, used as single agent, was more potent than MTX at promoting the overall survival of tumour-bearing mice." (PMID 35301407, 2022). "Targeting ATR itself, or its downstream mediators, CHK1 and WEE1, using small molecule inhibitors sensitised tumours to therapy in several clinical trials." (PMID 35301407, 2022). "Acting immediately downstream of ATR, targeting of Chk1 is effective in MYC-driven tumours including B-cell lymphomas owing to MYC-induced replication stress." (PMID 36505788, 2022). "There is growing evidence that ATR, CHK1 and the 9-1-1 complex are important drivers for tumor progression." (PMID 35456300, 2022). "Samples of P07-aRMS were obtained at the same timepoint but showed different events: the primary tumour exhibited an ATRX-deletion, whilst the metastasis harboured SNVs in ATR and RAF1, a biallelic BCOR-deletion, and a MYCN-amplification." (PMID 36182817, 2022). "In this regard, inhibitors of the ATR axis, including ATR, CHK1, and WEE1, have been used to effectively target tumor cells with increased replication stress." (PMID 35418189, 2022). "Treatment with BAY 1895344 significantly delayed tumor progression, suggesting that PAX7-FOXO1-harboring ARMS also respond to pharmacological ATR inhibition." (PMID 35879366, 2022). "Interestingly, low or moderate levels of TopBP1 correlate with normal ATR/Chk1 activation during stress, but TopBP1 overexpression has an inhibitory effect on ATR/Chk1 activation, which, in theory, would promote the resistance of tumor cells to DNA damage by suppressing apoptosis." (PMID 35897913, 2022). "In agreement, the results of Western blotting in tumor tissues showed that expression levels of γ-H2AX, p-ATR, RPA32, CHK1, and RAD51 were upregulated, and the phosphorylation level of CHK1 (p-chk1) was downregulated." (PMID 34660289, 2021). "IHC and Western blotting in tumor tissues showed that expression levels of γ-H2AX, p-ATR, RPA32, CHK1, and RAD51 were upregulated, and the phosphorylation level of CHK1 (p-chk1) was downregulated." (PMID 34660289, 2021).
tumor (continued). "Although ATR and CHK1 inhibitors have shown anti-tumor effects as monotherapy in preclinical studies, the clinical effects of these drugs most likely will be dependent on using the right combination therapies and biomarkers-guided patient classification." (PMID 34663432, 2021). "However, one must be mindful of the potential longer-term effects of sublethal targeting of tumor cells with ATR/Chk1 inhibitors that may promote genomic instability and clonal evolution, if these cells are allowed to accumulate replication stress-induced DNA damage but escape death." (PMID 34572908, 2021). "Similar to ATM, ATR inhibition in murine models of MLL-rearranged AML can prevent tumor growth and also reduce the tumor burden." (PMID 34732266, 2021). "The results remind us the correlation between VM formation and tumor grade and recurrence, suggesting a probable link between VM formation and ATM/ATR activation." (PMID 34483751, 2021). "Established tumours were treated with combination treatments of ionising radiation (IR), PARP inhibitor (olaparib) and ATR inhibitor (AZD6738/ceralasertib)." (PMID 32546832, 2020). "This study investigated the role of ATR on TAMs polarization in EBV-positive NPC, and the regulation mechanism of tumor genomic stability on the TME." (PMID 32917854, 2020). "The CHK1 kinase acts downstream of the ATR/ATM kinase, which is essential for embryonic development and tumour suppression." (PMID 32591500, 2020). "These promising results will serve as the basis for continued preclinical and clinical studies of ATR inhibitors in neoplasms with co-expression of MYB and ATR." (PMID 32001675, 2020). "Since tumour cells rely heavily on the DDR pathway and the MRN complex, inhibiting the function of ATR inhibits the growth of colorectal cancers in vitro and has the potential to increase chemoradiation sensitivity." (PMID 30769804, 2019). "Inhibiting the DNA damage response (DDR) by ATR, which activates CHK1, triggers a durable anti-tumour immune response when used in combination with radiation." (PMID 31500184, 2019). "Oncogene-induced replication stress serves as a tumour specific vulnerability and rationale for the clinical development of inhibitors targeting the DNA damage response (DDR) kinases (CHK1, ATR, ATM and WEE1)." (PMID 31500184, 2019). "In both mouse and human non-tumor cells, genotoxic stress and inhibition of DNA replication via the DNA damage pathway through ATM or ATR protein kinases, leads to increased surface expression of NKG2D-ligands." (PMID 29973929, 2018). "This dependency is further emphasized by the fact that ATR and CHK1 levels often are upregulated in neoplasms and are thought to promote tumour growth." (PMID 29720710, 2018). "Depletion of ATR or CHK1, e.g., using siRNA enhanced tumour cell killing by a wide range of genotoxic agents." (PMID 28448462, 2017). "To confirm that the increased of γH2Ax staining, observed in 8-QA treated tumors, was not due to the blocking of cells in S phase, we analyzed on treated tumor samples, phosphorylated CHK-1, which is known to be ATR dependent." (PMID 29221170, 2017). "Both ATR bound to tumor cells with comparable MFI; however ATR made with less T cell binding complexes demonstrated a reduced MFI compared to 1:1 ATR staining." (PMID 27602488, 2016). "ATR stably bound to effector and target cells and induced specific effector-target cell conjugate formation resulting in redirected lysis of human CD19+ tumor cells." (PMID 27602488, 2016).
tumor (continued). "Here, ATR and ATM indeed cooperated in their response to chemotherapeutics in different tumor contexts." (PMID 26208482, 2015). "Our studies indicated that the combination of ATR inhibitor and high LET carbon irradiation provided very effective tumor control." (PMID 26286029, 2015). "Therefore, the ATR kinase signaling may be a tumor suppressor mechanism." (PMID 26438152, 2015). "In this dataset, expression of ERH mRNA was correlated with expression of ATR mRNA in 444 liver tissues containing HCC and non-tumor tissues." (PMID 25880358, 2015). "We analyzed the protein expression of MRE11, MDC1, ATM, ATR and BRCA1 by immunohistochemistry (IHC) in 97 SOC samples, and correlated with clinical parameters including age, tumor grades, clinical stage, status of menstruation and chemotherapy." (PMID 24752797, 2014). "The tumor suppressors ARF and ATR, as well as the transcription factor SMAD, mediate a cytostatic response upon DNA damage or TGFβ signaling." (PMID 22443451, 2012). "Although previous studies documented that FdUrd activates the ATM- and ATR-dependent checkpoints, these studies did not compare the effects of ATM and ATR depletions on the survival of tumor cells exposed to both agents." (PMID 22194930, 2011). "In the Netherlands, observed putative PGVs in dominant genes that do not match the tumor type (ATR, CHEK2 (3x), SDHA and MITF) are normally not reported back to the patient, except if there is a matching personal and/or familial history." (PMID 41168197, 2025). "This combinatorial regimen induces G2-phase cell cycle arrest, apoptosis, and extensive DNA damage; however, ATR inhibition alone significantly impairs xenograft tumour growth, with no additional therapeutic advantage conferred by PARP inhibition." (PMID 40256842, 2025). "ATR inhibition also activated STING and increased tumor expression of MHC-I." (PMID 40422251, 2025). "Tackling these resistance mechanisms may require combination approaches, such as pairing PARP inhibitors with ATR or WEE1 inhibitors to prevent replication stress recovery, or with checkpoint inhibitors to enhance tumor immunogenicity." (PMID 40842586, 2025). "Incorporating spatial and single-cell data into therapeutic design will be essential for predicting which tumor regions—and which subclones—are likely to respond to PARP or ATR inhibition, and for identifying combination strategies that overcome spatially restricted immune escape." (PMID 41373427, 2025). "Also, increased expression of γ-H2AX, p-ATR, RPA32, CHK1, and RAD51 were noted in tumour tissues, as well as a decrease in phosphorylation of the CHK1 signalling molecule (p-chk1)." (PMID 41228271, 2025). "The heterogeneity of clinical outcomes across tumor types indicates that ATR inhibitors are unlikely to serve as broadly effective anticancer agents." (PMID 41409249, 2025). "CHK1/2, serving as key downstream effector molecules of the ATR and ATM signaling pathways, primarily trigger cell cycle arrest by precisely regulating G1/S and G2/M checkpoints, thereby exerting core regulatory functions in the DDR network of tumor cells." (PMID 41473689, 2025). "Inhibiting Chk1 and Chk2, highly conserved serine/threonine kinases and key downstream targets of ATR and ATM, respectively, could disrupt the initiation of G1/S and G2/M checkpoints, impair DNA repair mechanisms and promote apoptosis in tumor cells." (PMID 40422251, 2025). "The effects of ATR inhibition on the whole immune cell population (not just those cells located in the tumor) should also be considered." (PMID 39235982, 2024).